ESR1 (estrogen receptor 1)
Diseases named in the same sentence as ESR1 in open-access papers (continued):
Sharing a sentence is not in itself a finding about the gene and the disease.
endometrial cancer (continued). "Furthermore, via the analysis of TCGA-STAD database by an online tool GEPIA, we found a positive correlation between high expression of ESR1 and survival rate in endometrial cancer." (PMID 40342082, 2025). "Whether ZMIZ1 exerts similar transcriptional regulatory roles in endometrial cancer remains an important question, particularly with respect to its influence on ESR1-driven gene programs." (PMID 41321319, 2025). "Studies have found that 11 ESR1 circular isoforms are expressed in endometrial cancer tissues, and detecting tumor-specific circular isoforms of the ESR1 gene may become a molecular marker for early diagnosis of endometrial cancer." (PMID 41299798, 2025). "Estrogen receptor 1 (ESR1) plays a key role in estrogen-dependent endometrial cancer." (PMID 41299798, 2025). "Dysregulation of ESR1 cofactors, exemplified by ZMIZ1, may underline a spectrum of estrogen-dependent conditions, including endometriosis, endometrial cancer, and other hormone-driven disorders." (PMID 41321319, 2025). "Given that the expression level of ESR1 is negatively correlated with the clinical stages of endometrial cancer, it is speculated that ESR1 may be involved in the occurrence or differentiation process of cancer stem cells." (PMID 40342082, 2025). "ESR1 mutations do not seem to be involved in the mechanisms of resistance to AI or M in HR + endometrial cancer." (PMID 37924026, 2023). "In endometrial cancer, there is currently no interest in testing for ESR1 mutations prior to the introduction of these new SERDs, given the results of this study." (PMID 37924026, 2023). "Most endometrial cancer cell lines do not express ESR1 and harbor ARID1A mutations as well as other cancer-driver mutations." (PMID 35326450, 2022). "Although estrogen receptor 1 plays an important role in hormonal responses in estrogen-sensitive tissues, studies demonstrated that its cellular abundance has little significance in prognostic relevance of endometrial cancer." (PMID 29464034, 2018). "The expression of PGR and ESR1 is strongly correlated with the prognosis of endometrial cancer." (PMID 29843645, 2018). "Secondly, only two polymorphisms (PvuII and XbaI) in ESR1 gene were evaluated in the previous meta-analysis, while the other common polymorphisms potentially related to endometrial cancer risk were not studied." (PMID 23593326, 2013). "The ESR1 variants did not, however, seem to affect myometrial invasion or endometrial cancer survival." (PMID 19319135, 2009). "Using a comprehensive tagging approach of common variation in the ESR1 and EGF genes, we assessed whether common variants in the genes affected endometrial cancer risk, myometrial invasion, or endometrial cancer survival." (PMID 19319135, 2009). "Since altered ER function could have impact on the risk of endometrial cancer, the estrogen receptor alpha gene (ESR1) is a plausible endometrial cancer candidate gene which has been investigated in a few studies." (PMID 18990228, 2008). "Notably, a related study on cytokine regulation of ERα expression in endometrial cancer cells highlighted that IL-17 A could enhance ERα expression by stimulating ESR1 transcription." (PMID 40665298, 2025). "Contrary to this, a higher mRNA expression of ESR1 in HOSC could be attributed to a ligand-independent action of ESR1 as previous studies in human endometrial cancer cells, have reported higher estrogen-independent activity of ESR1 in D538G mutants compare to their wild-type counterparts." (PMID 39342193, 2024). "Moreover, ESR1 amplification might be one mechanism for ER over-expression in endometrial carcinoma." (PMID 37033258, 2023). "However, the experimental investigation of ESR1 mutations in endometrial cancer has not been performed." (PMID 33535614, 2021). "To further confirm the role of ESR1 in endometrial cancer, we selected the endometrial cancer cell lines Ishikawa (ISK, ESR1 positive) and RL95-2 (ESR1 weak) for further investigation." (PMID 40342082, 2025).
endometrial cancer (continued). "DNA methylation in the promoter region of the ERα gene ESR1 can silence its expression, which is observed in several cancer types, including ovarian and endometrial cancers." (PMID 39796024, 2024). "Estrogen, through its receptors ERα (ESR1) and ERβ (ESR2), plays a pivotal role in endometrial cell proliferation, and aberrant estrogen signaling can contribute to endometrial cancer development." (PMID 38910609, 2024). "The analysis of the Uterine Corpus Endometrial Carcinoma database in the TCGA repository showed that the WNT4 gene was altered in 13 (3%) samples, while ESR1 was altered in 60 (14%) of 440 queried patient profiles." (PMID 37835474, 2023). "Five most significant genes were selected, including L1CAM (L1 cell adhesion molecule), PRKCI, ESR1, CDKN2A and VIM, to construct a prognostic model for endometrial cancer." (PMID 34659539, 2021). "In human Ishikawa endometrial cancer cells, MET treatment (60 μM) decreased cell numbers and elicited distinct temporal changes in ESR1, KLF9, PGR, PGR-B, KLF4, DKK1, and other tumor biomarker mRNA levels." (PMID 32046384, 2020). "The estrogen-agonistic effect of tamoxifen in endometrial cancers can also be explained by the expression of G-protein coupled estrogen receptor 1 (GPER-1), a membrane-bound estrogen receptor for which tamoxifen and other “antiestrogens” are pure agonists." (PMID 32906618, 2020). "In contrast, low ESR1 expression and high ESR2 expression subtypes present proliferative phenotype in hepatocellular cancer and mitotic phenotypes in endometrial carcinoma." (PMID 32536040, 2020). "To identify SOX2-positive endometrial cancer cells for further oncogenic analysis, we checked SOX2 expression in Ishikawa (ESR1-positive) and its descendant Ishikawa-02 (ESR1-negative) cells." (PMID 30510261, 2018). "Expression of PGR (PR-A and PR-B) and ESRs (ESR1 and ESR2) has been reported as prognostic factors for endometrial carcinoma." (PMID 29843645, 2018). "Many previous genetic studies have suggested that ESR1 gene polymorphisms may play an important role in endometrial carcinogenesis, while other studies found no convincing evidence of these polymorphisms in increasing endometrial cancer susceptibility." (PMID 23593326, 2013). "We found that ATAD2 copy-number, ESR1 expression and E2F1 expression explained 77% of the variation in ATAD2 expression in endometrial cancer, and each of the predictor variables remained significantly associated with ATAD2 expression in the adjusted model." (PMID 23393560, 2013). "We analyzed estrogen receptor alpha (ESR1) expression in endometrial cancer (EC) tissues and adjacent noncancerous tissues." (PMID 40342082, 2025). "Three of these NHRs – progesterone receptor (PGR), estrogen receptor 1 (ESR1), and androgen receptor (AR) – have been previously reported to lose expression in subsets of endometrial carcinomas, which confirms that our approach can capture NHRs known to lose expression in endometrial carcinoma." (PMID 32894083, 2020). "The ESR1 gene did not seem to significantly affect myometrial invasion or endometrial cancer survival." (PMID 19319135, 2009). "Consistent with the established literature, endometrial cancers that lose both ESR1 and PGR expression (DN, for double negative) have poor 5-year survival compared with cancers that do not lose both ESR1 and PGR (DP, for double positive) (q-value = 1.23 × 10− 6, log-rank test)." (PMID 32894083, 2020). "However, structural genetic alterations of ESR1 have not been suggested to play a role in endometrial cancer carcinogenesis." (PMID 27160768, 2016).
endometrial cancer (continued). "We aimed towards capturing the entire common variation in the ESR1 and EGF genes by genotyping a dense set of markers in 92 Swedish controls and then selecting haplotype tagging SNPs (tagSNPs) that were genotyped in 713 Swedish endometrial cancer cases and 1567 Swedish controls." (PMID 19319135, 2009). "To investigate if this molecularly enhanced progestin therapy can be applied to advanced endometrial cancer patients with ERα and PR negative tumors; we generated ERα null endometrial cancer cell lines by applying novel CRISPR-Cas9 technology to delete ERα at the genomic level (ESR1)." (PMID 26859414, 2016).
prostate carcinoma (359 papers, 2004 to 2026). A carcinoma that arises from epithelial cells of the prostate gland. "In patients with recurrence, there was an increased expression of ERG and ESR1, which is linked to aggressive prostate cancer." (PMID 40691608, 2025). "In 1999, ESR1 was first reported to be associated with metastatic prostate cancer lesions, including those in lymph nodes." (PMID 40868045, 2025). "Research findings suggest a potential association between ESR1 and the risk of late-onset prostate cancer." (PMID 39863836, 2025). "Several polymorphisms in ESR1 gene, such as PvuII (rs9340799 A>G) and XbaI (rs2234693 C>T), have been studied to a assess their causal relationships with prostate cancer." (PMID 23805288, 2013). "Generally, ESR1 is implicated in prostate cancer susceptibility by stimulating aberrant prostate growth, controlling prostate cell growth and programming prostate cell death." (PMID 23805288, 2013). "Many published data on the association between single nucleotide polymorphisms (SNPs) in the ESR1 gene and prostate cancer susceptibility are inconclusive." (PMID 23805288, 2013). "Many investigations have demonstrated that prostate cancer risk was associated with the ESR1 gene polymorphism." (PMID 23805288, 2013). "Such relationship can provide a more comprehensive mechanism of how ESR1 mutations function in the development of prostate cancer, as well as promise a more effective treatment for prostate cancer." (PMID 23805288, 2013). "To explore the association between ESR1 gene polymorphisms and prostate cancer risk, we performed a meta-analysis on 2,165 prostate cancer cases and 3,361 controls." (PMID 23805288, 2013). "Several ESR1 gene polymorphisms have been identified as candidates for prostate cancer susceptibility and among these, ESR1 PvuII and XbaI SNPs were suggested to possess significant associations with the development of prostate cancer." (PMID 23593326, 2013). "Such relationship will shed light on a comprehensive functional profiling of ESR1 gene for better understanding of the biological processes associated with prostate cancer formation and progression." (PMID 23805288, 2013). "This is the first meta-analysis exploring the relationship between prostate cancer and the ESR1 gene polymorphisms." (PMID 23805288, 2013). "The findings of this meta-analysis on the correlation between ESR1 XbaI (A>G) and prostate cancer risk are summarized." (PMID 23805288, 2013). "Ten studies involved the correlations between ESR1 PvuII (C>T) polymorphism and prostate cancer risk." (PMID 23805288, 2013). "The associations between ESR1 XbaI (A>G) polymorphism and prostate cancer risk were investigated in six studies." (PMID 23805288, 2013). "Some meta-analyses suggest that ESR1 polymorphisms may increase the risk of prostate cancer in American and Indian populations." (PMID 35594510, 2022). "ESR1 has the effects of stimulating abnormal prostate growth, controlling prostate cell growth and programming prostate cell death, and these effects are associated with prostate cancer susceptibility." (PMID 35594510, 2022). "The pooled analyses showed that ESR1 XbaI (A>G) polymorphism might be associated with increased risk of prostate cancer in population-based and PCR-RFLP subgroups." (PMID 23805288, 2013). "Moreover, we also performed a pooled analysis for all eligible case-control studies to explore the role of ESR1 codon 10 (T>C), codon 325 (C>G), codon 594 (G>A) and +261G>C polymorphisms in prostate cancer susceptibility." (PMID 23805288, 2013). "Therefore, we performed a meta-analysis of all eligible case-control studies with prostate cancer risk and aimed to reveal a more precise relationship between ESR1 gene polymorphisms and prostate cancer susceptibility." (PMID 23805288, 2013). "However, further studies are still needed to warrant and validate the association between ESR1 gene polymorphism with other genetic polymorphisms and prostate cancer risk." (PMID 23805288, 2013).
prostate carcinoma (continued). "Meta-analysis of the association between ESR1 PvuII (C>T) polymorphism and prostate cancer risk." (PMID 23805288, 2013). "The results showed that ESR1 PvuII (C>T) polymorphism might increase the risk of prostate cancer among Asian populations, especially among Indian population." (PMID 23805288, 2013). "Recently, several ESR1 gene polymorphisms have been identified as candidates for prostate cancer susceptibility and among these, ESR1 PvuII (rs2234693 C>T) and XbaI (rs9340799 A>G) polymorphisms were suggested to possess significant associations with the development of prostate cancer." (PMID 23805288, 2013). "Meta-analysis of the association between ESR1 XbaI (A>G) polymorphism and prostate cancer risk." (PMID 23805288, 2013). "First, the sample size is still relatively small and may not provide sufficient power to estimate the association between ESR1 gene polymorphisms and prostate cancer risk." (PMID 23805288, 2013). "Furthermore, identification of common polymorphisms in the ESR1 gene may be useful in early diagnosis of prostate cancer, allowing patients to receive timely and effective anti-cancer therapies." (PMID 23805288, 2013). "In summary, this meta-analysis suggested that ESR1 PvuII (C>T) polymorphism may be a potential risk factor for prostate cancer among Asian populations, especially among Indian population; while ESR1 XbaI (A>G) polymorphism may increase the risk of prostate cancer among American population." (PMID 23805288, 2013). "Results from the current meta-analysis indicate that ESR1 PvuII (C>T) polymorphism may be a risk factor for prostate cancer among Asian populations, especially among Indian population; while ESR1 XbaI (A>G) polymorphism may increase the risk of prostate cancer among American population." (PMID 23805288, 2013). "BRCA2, DAB2IP, and the DNA-PKcs inhibitor NU7441 are prostate cancer-related markers, while the methylation of ESR1 and MYOD1 and expression of SEPT9 correlate with radiotherapy response in cervical cancer." (PMID 40277781, 2025). "ESR1 influences disease progression by activating stroma, stimulating stem/progenitor prostate cancer, and inducing TGF-β." (PMID 37965470, 2023). "CTC ESR1 mutational heterogeneity and CTC genomic relationship to metastatic and primary tissue have been documented primarily in breast and prostate cancer." (PMID 34866317, 2022). "(b) reads per genome coverage (RPGC)-normalized aggregate genome tracks comparing HyDrop-ATAC and bulk ATAC-seq profiles of human MCF-7 and prostate cancer-3 (PC-3) cell lines around the estrogen receptor 1 (ESR1) locus, scaled to maximum of all four samples." (PMID 35195064, 2022). "In line with our prediction, studies show that ICT can target ESR1 and AR to control the growth of advanced breast and prostate cancer, which confirms the predictive accuracy of our approach." (PMID 33460401, 2021). "Data were also produced demonstrating that prostate cancer cells can use alternative nuclear receptors signaling pathway, such as ESR1 instead of AR signaling, to propagate." (PMID 32041153, 2020). "Here we showed that the estrogen signaling, and in particular ESR1, increased in NE-like samples from our cohort and in a model of prostate cancer organotypic slice culture (OSC)." (PMID 32041153, 2020). "Secondly, the KEGG enrichment analysis conducted by DAVID identified three ESR1-related signaling pathways and prostate cancer pathway, which were significantly altered by naringenin-mediated proteins." (PMID 30918758, 2019). "It is worth emphasizing that estrogen receptor 2 (ESR2/ERβ) was highly expressed, while estrogen receptor 1 (ESR1/ERα) had a relatively low level of expression or was almost undetectable in prostate cancer lines." (PMID 30361641, 2018).